TIMP1 (TIMP metallopeptidase inhibitor 1)
Diseases named in the same sentence as TIMP1 in open-access papers (continued):
Sharing a sentence is not in itself a finding about the gene and the disease.
Parkinson disease (8 papers, 2012 to 2025). A progressive degenerative disorder of the central nervous system characterized by loss of dopamine producing neurons in the substantia nigra and the presence of Lewy bodies in the substantia nigra and locus coeruleus. "The results showed that TIMP1 was enriched in pathways including allograft rejection, glycosphingolipid biosynthesis ganglion series, citric acid cycle recycling, and Parkinson's disease." (PMID 41393260, 2025). "Several studies have reported elevated levels of TIMP-1 in the CSF of patients with AD and Parkinson’s disease (PD), indicating a protective effect of TIMP-1." (PMID 38891891, 2024). "Lorenzl et al12 measured the levels of TIMP‐1 in CSF samples of patients with Parkinson's Disease, AD, Huntington's Disease and amyotrophic lateral sclerosis, and demonstrated that elevated TIMP‐1 levels were observed in all participants." (PMID 32431079, 2020). "While it is also interesting that TIMP1 has been suggested as a biomarker in biofluids in both Parkinson’s disease and AD, further exploration of TIMP1 could be especially fruitful in understanding the early drivers of BPSD." (PMID 38575567, 2024).
sarcopenia (8 papers, 2022 to 2026). Progressive decline in muscle mass due to aging which results in decreased functional capacity of muscles. "We identified seven robust protein signatures (LRG1, CST3, TIMP1, C2, ITIH1, AMBP and LYZ) that showed consistent significant associations with sarcopenia components in both cohorts." (PMID 41782349, 2026). "Another study evaluating serum MMP9 levels in 88 sarcopenic patients aged 65 and over showed that serum MMP9/tissue inhibitor of metalloproteinase 1 (TIMP1) had similar performance as a sarcopenia biomarker to the SARC-F questionnaire (AUC = 0.67)." (PMID 40008206, 2024).
aortic stenosis (7 papers, 2015 to 2026). Aortic valve stenosis is a aortic valve disease caused by the incomplete opening of the aortic valve. "A study evaluating atrial remodeling in aortic stenosis patients with chronic AF showed a decrease in the MMP16/TIMP4 ratio in patients with AF along with an increased serum TIMP1 and TIMP2 proteins." (PMID 36312240, 2022). "MMP2 degrades troponin I in IRI ischemia–reperfusion injury, while in aortic stenosis, TIMP1 and TIMP2 are related to fibrosis." (PMID 34449561, 2021). "This study indicates an atrial matrix remodeling in aortic stenosis patients with chronic AF submitted to valve replacement while suggesting TIMP1 and TIMP2 as biomarkers of disease, readily available with peripheral blood sampling." (PMID 33129260, 2020). "Serum TIMP1 could be a marker of adverse outcomes in aortic stenosis, in addition to conventional echocardiography." (PMID 33129260, 2020). "TIMP1 could be a marker of adverse outcomes in aortic stenosis, in addition to conventional echocardiography." (PMID 33129260, 2020). "Concerning aortic stenosis severity, Aortic Valve Maximum and Mean Gradients were negatively correlated with collagen type I gene expression, collagen type I/III ratio, and serum TIMP1 protein levels." (PMID 33129260, 2020). "In addition, serum MMP-9, but also MMP-3 and TIMP-1, was correlated with invasive aortic PWV measurements in patients with aortic stenosis." (PMID 29070037, 2017).
Breast Invasive Carcinoma (7 papers, 2008 to 2026). "We found that TIMP-1 expression was significantly increased in invasive breast carcinoma and ductal breast carcinoma compared with normal breast tissues." (PMID 27130446, 2016). "TCGA analysis of TGF-β target genes (e.g., COL1A1, COL3A1, COL5A2, COL6A1, COL6A3, TIMP1, and CTGF) further identified overactivation of TGF-β signaling pathway in a broad spectrum of solid tumors, in particular in breast invasive carcinoma and pancreatic adenocarcinoma tissues." (PMID 37328484, 2023).
Cerebral ischemia (7 papers, 2017 to 2025). Restriction of arterial blood supply to the brain associated with insufficient oxygenation to support the metabolic requirements of the tissue. "Previous studies have demonstrated lower BBB permeability and infarction following cerebral ischemia in TIMP1-overexpressing transgenic mice relative to their wild-type counterparts." (PMID 35163322, 2022). "Moreover, astragalus polysaccharides and saponins can inhibit MMP-9 expression and enhance TIMP1 expression after cerebral ischemia/reperfusion (I/R) injury in mice." (PMID 28831024, 2017).
chronic heart failure (7 papers, 2011 to 2023). "An early study shows that increased TIMP-1 levels is a risk factor of mortality among congestive heart failure patients." (PMID 35284430, 2021). "Previous studies, primarily in chronic heart failure patients, have also found inverse associations between TIMP-1 levels and functional outcomes, including impaired exercise oxygen consumption, increased cardiovascular endpoints, and shorter 6 min walk test distance." (PMID 36737697, 2023). "In patients, circulating levels of OPN, PAI-1, and TIMP-1 increase with the progression of chronic heart failure and PH." (PMID 21789188, 2011).
colorectal adenoma (7 papers, 2015 to 2025). An adenoma that arises from the colon or rectum. "Second, due to the small number of included studies, we only focused on the diagnostic value of TIMP-1 between CRC and healthy controls, though some other studies have raised concerns about the role of TIMP-1 in patients with colorectal adenoma." (PMID 30458003, 2018). "TIMP1 sustains the major diagnostic and prognostic implications for the progression of CRC, particularly, serving as a useful marker for differentiating CRC from colorectal adenomas (Łukaszewicz-Zając and Mroczko 2021)." (PMID 39325241, 2025). "Serum TIMP-1 is useful in differentiating between CRC and colorectal adenomas, whereas M-CSF and CRP are independent prognostic factors for the survival of patients with CRC." (PMID 34071492, 2021).
idiopathic pulmonary fibrosis (7 papers, 2011 to 2024). Idiopathic pulmonary fibrosis (IPF) is a nonneoplastic pulmonary disease that is characterized by the formation of scar tissue within the lungs in the absence of any known cause. "Bleomycin-induced idiopathic pulmonary fibrosis (IPF), a disease characterized by chronic, progressive scarring of the lungs associated with a decline in respiratory function, induces the expression of both TIMP1 and TIMP2 in the alveolar and interstitial compartments." (PMID 36624735, 2022).
injury (7 papers, 2011 to 2023). Damage inflicted on the body as the direct or indirect result of an external force, with or without disruption of structural continuity. "The TIMP‐1 has been associated with survival in several other critical diseases, including traumatic brain injury, cerebral infarction, graft versus host disease and acute respiratory failure." (PMID 31932967, 2021). "In our present study, we found increased expression of TGF-β1 protein as well as TIMP-1, collagen I, and collagen III, which have been proven to be associated with fibrosis formation after liver injury." (PMID 37389959, 2023). "Thus, the obtained data indicate that anti-Timp1-siRNA reduces the severity of LPS-induced acute lung injury." (PMID 36675165, 2023). "Animal studies have reported that TIMP-1 and TIMP-2 are highly expressed in hepatic fibrosis and hyperoxia-induced acute lung injury." (PMID 24944589, 2014). "In addition to TIMP-1, astrocyte expression of TIMP-2 has also been described in vivo following astrocyte activation after brain injury." (PMID 21631912, 2011). "We designed an effective chemically modified anti-TIMP1 siRNA and showed that Timp1 silencing correlates with a decrease in the pro-inflammatory cytokine IL6 secretion in cultured macrophage cells and reduces the severity of LPS-induced acute lung injury in a mouse model." (PMID 36675165, 2023). "In addition to these classic biomarkers, the newest ones have shown promising results for the diagnosis of early-stage kidney injury: cystatin C, KIM-1, NAG, NGAL, β2-microglobulin, osteopontin, TIMP-1, GST-α, without being implemented in clinical practice." (PMID 36676974, 2022).
metastatic melanoma (7 papers, 2013 to 2025). A melanoma that has spread from its primary site to another anatomic site. "However, the association of TIMP-1 with immunogenic responses in cancers, particularly in metastatic melanoma, encompassing features of DC activation such as antigen presentation, remains unexplored." (PMID 38777826, 2024). "In addition to recombinant TIMP-1, a plasmid vector encoding human TIMP-1 cDNA (TIMP-1pDNA), administered intramuscularly to female mice with B16-F10 metastatic melanoma, causing a spike in serum human TIMP-1, was also used in the studies." (PMID 39594665, 2024). "Our research reveals a correlation between high TIMP1 levels in metastatic melanoma and increased CD8 + T cell infiltration and survival." (PMID 38777826, 2024). "In this study, by integrating spatial-immune monitoring from clinical datasets and reverse translation, we delved into a multidisciplinary study of TIMP-1’s role in the immunogenic context of metastatic melanoma, a cornerstone model for ICT research." (PMID 38777826, 2024). "Our study offers evidence for a novel immune function for TIMP-1, backed by its link with immunogenic characteristics of metastatic melanoma and favorable prognosis." (PMID 38777826, 2024). "For this purpose, we injected metastatic melanoma 4C11+ cell line, wild-type and silenced for Timp1, in the subcutaneous tissue of female C57BL/6 mice and observed tumor growth." (PMID 28430130, 2017). "As previously discussed, AKT is also important and was shown to be acting independently of Timp1 in the metastatic melanoma 4C11+ cell line." (PMID 28430130, 2017). "In addition, Kluger and colleagues identified TIMP1 as a plasma marker in patients with metastatic melanoma." (PMID 23522389, 2013). "Notably, TIMP1 emerged as a strong prognostic marker in both primary and metastatic melanoma." (PMID 40943183, 2025). "Mariana Toricelli found that Timp1 confers cell survival through activation of the PDK1 pathway and that Timp1 and AKT cooperate to confer resistance to anoikis in metastatic melanoma cells." (PMID 37626132, 2023). "We also observed that the simultaneous deletion of Timp1 and AKT prevents more efficiently cell survival, providing a possible new therapeutic strategy for metastatic melanoma." (PMID 28430130, 2017). "Our data provides evidence that Timp1 confers cell survival by activating PDK1 signaling pathway and that Timp1 and AKT have synergistic effects to confer anoikis resistance in metastatic melanoma cells." (PMID 28430130, 2017). "Increased transcript level of Timp1 and CD63 was shown in different human metastatic melanoma cell lines compared to primary human melanocytes." (PMID 23522389, 2013). "Taken together, this finding indicates that simultaneous inhibition of Timp1 and AKT might be a potential strategy in the fight against metastatic melanoma." (PMID 28430130, 2017). "Therefore, we hypothesize a functional link for TIMP-1 influencing antigen presentation and the generation of cytolytic CD8 + T cells in LNs of metastatic melanoma patients, which may stem from its cellular and molecular functions on local immune cells." (PMID 38777826, 2024).
myocarditis (7 papers, 2013 to 2025). Myocarditis is a condition that is characterized by inflammation of the heart muscle (myocardium). "Anti-TIMP1 antibody treatment reduced virus-induced myocarditis in mice." (PMID 39970910, 2025). "The ratio of TIMP-1/MMP-1 or MMP-3 expression was significantly increased (P < 0.05) indicating an increase of deposition of collagen proteins at the later stage of CVB3 myocarditis." (PMID 24023968, 2013).
papillary thyroid carcinoma (7 papers, 2015 to 2026). "Recent research indicated that Angiopoietin-1 played a role in lymph node metastasis and invasiveness of papillary thyroid carcinoma TIMPs, which comprise a family of four protease inhibitors: TIMP1, TIMP2, TIMP3, and TIMP4." (PMID 36672532, 2022). "We previously reported an upregulation of the clock transcript BMAL1, correlating with TIMP1 expression in fresh-frozen samples from papillary thyroid carcinoma (PTC)." (PMID 25868389, 2015). "Through qRT-PCR experiments, it was confirmed that the expressions of TIMP1 and DPP4 were higher in thyroid papillary carcinoma than in normal PTC cells." (PMID 42073588, 2026). "According to the ROC results, TIMP1, LOX, CD276, IFNA1, TLR2, and POSTN were considered to play a more critical role in malignant papillary thyroid cancer or immature cancer of papillary thyroid cancer." (PMID 36120433, 2022). "TIMP1, LOX, CD276, IFNA1, TLR2, and POSTN have different expressions in PTCs, which lead to the various clinical courses of a woman older than 55 years old with papillary thyroid cancer." (PMID 36120433, 2022).
psoriasis (7 papers, 2010 to 2023). An autoimmune condition characterized by red, well-delineated plaques with silvery scales that are usually on the extensor surfaces and scalp. "The levels of the TIMP1 protein in the blood serum increase after the occurrence of a psoriasis rash to a degree that correlates with the severity of the disease." (PMID 33419373, 2020). "In psoriasis, TIMP-1 and TIMP-3 are present in the inflammatory infiltrate and in the endothelial cells of the papillary dermis." (PMID 33419373, 2020). "Gene interaction analyses highlighted IFNG, IL4, IL10, MMP9 and TIMP1 in IBD; IL10, IL13 and PTGS2 in psoriasis; IL8, IL10 and PTGS2 in RA." (PMID 20444268, 2010). "Psoriasis shares a systemic production of inflammatory mediators, which are key regulators of the production of matrix metalloproteinase (MMP9) and its inhibitor TIMP1." (PMID 34715781, 2021). "A representative proinflammatory cytokine, IL-18, has been classified as a biomarker for the activity of psoriasis, in addition to other cytokines including transforming growth factor beta 1 (TGF-β1), tissue inhibitor of metalloproteinase 1 (TIMP-1), and matrix metalloproteinase 1 (MMP-1)." (PMID 26901187, 2016).
squamous cell carcinoma (7 papers, 1998 to 2025). A carcinoma arising from squamous epithelial cells. "Some high‐grade tumour cells also show positive cytoplasmic staining of TIMP1, particularly squamous cell carcinomas and adenocarcinomas with sarcomatous features." (PMID 37759102, 2023). "In adenocarcinoma, there was an increase in TIMP1 expression 100 days after surgery compared to the baseline expression, while in squamous carcinoma, there was a decrease in TIMP1 expression 100 days after surgery." (PMID 37509417, 2023). "The purpose of this study was to investigate MMP-13 and TIMP-1 expression in squamous cell carcinomas of the head and neck and to relate these levels of expression to histologic patterns of invasion." (PMID 15291964, 2004). "The expression of MMP-13 and TIMP-1 appears to play an important role in determining the invasive capacity of squamous cell carcinomas of the head and neck." (PMID 15291964, 2004). "Squamous cell carcinoma is linked to the expression of MARCKS, CD36, DAB2, ENPEP, and TIMP1." (PMID 40565366, 2025). "In squamous cell carcinoma H1703 cells, at 24 h, MMP-2, MMP-9, TIMP-1, and TIMP-2 in the MG showed higher expression than in the CONT." (PMID 31601869, 2019).
brain injury (6 papers, 2020 to 2025). Acute and chronic (see also brain INJURIES, CHRONIC) injuries to the brain, including the cerebral hemispheres, CEREBELLUM, and brain STEM. "Higher TIMP-1 levels were associated with increased mortality rates after traumatic brain injury presenting a prognostic biomarker in TBI patients." (PMID 32258173, 2020). "In severe traumatic brain injury (sTBI), Timp1, acting as an inflammatory cytokine, has been closely linked to disease severity." (PMID 38728287, 2024). "Increased TIMP-1 levels in serum has also been proposed as a prognostic biomarker of mortality in brain trauma injury patients." (PMID 33603109, 2021). "A mouse experiment shows that TIMP1 regulates endothelial barrier integrity by interacting with CD63/integrin β1 complex and has a protective effect on BBB breakdown induced by traumatic brain injury." (PMID 40604895, 2025).
cardiomyopathy (6 papers, 2014 to 2023). A disease of the heart muscle or myocardium proper. "The present findings demonstrate that in a rat model of T2DM-induced cardiomyopathy, there is evidence of an association between damage of the cardiac contractile unit—sarcomere and desmin—and the iNOS/mTOR/TIMP-1/collagen axis of fibrosis." (PMID 35625721, 2022). "Both upregulation of Timp1 and downregulation of Mmp9 in cardiac fibroblasts have been proved to preserve cardiac functions and inhibit fibrosis in cardiomyopathy." (PMID 33061247, 2020). "Levels of TIMP-1 and TIMP-2 were also higher in Tc+ stage CD compared to Tc+ stages A and B. Like other cardiomyopathies, Chagas heart disease involves substantial tissue remodeling and progressive fibrosis; the changes seen in MMP and TIMP levels are a reflection of the severity of these processes." (PMID 25275382, 2014). "However, the association between damage of the cardiac contractile unit—desmin and neighboring sarcomere—and the iNOS/mTOR/TIMP-1/collagen axis of fibrosis in rats with T2DM-induced cardiomyopathy has not been previously investigated." (PMID 35625721, 2022). "BNP, NTproBNP, troponin I, MMP-2, TIMP-1, and TIMP-2 levels rose with increasing severity stage but did not distinguish between Chagas cardiomyopathy and other cardiomyopathies." (PMID 25275382, 2014). "We showed significant elevations in BNP, NTproBNP, Troponin I, MMP-2, TIMP-1 and TIMP-2 among Tc+ individuals with cardiomyopathy compared to those without heart disease, findings consistent with previous studies." (PMID 25275382, 2014).
Chronic colitis (6 papers, 2019 to 2024). A chronic inflammatory disease of the large intestine (colon, cecum and rectum). "TIMP1 deficiency can alter inflammation and attenuate fibrosis deterioration in acute and chronic colitis mouse models." (PMID 38778086, 2024). "We used qRT-PCR analysis to test the expression of MMPs known to be regulated in CD and showed that MMP-9 and MMP-2 were upregulated, but TIMP-1 was downregulated after the TFA treatment in the TNBS-induced chronic colitis mice model." (PMID 35002710, 2021). "Given the hub position of Mmp9 and Timp1 and the formation of a highly connected cluster of MMPs in the core gene-retrieved network, the changes in the MMPs profile can be involved in the regulation of malignant transformation of colon tissue during chronic colitis." (PMID 36901742, 2023). "DSS-induced chronic colitis attenuated biliary septal fibrosis, which may be attributed to less BA accumulation mediated inhibition of activated HSCs (Col1a1, Col1a2, Col3a1 and Timp1) without affecting PFs in Mdr2−/− mice." (PMID 37280200, 2023).
clear cell renal cell carcinoma (6 papers, 2018 to 2023). "A recent study showed that high TIMP1 mRNA was associated with a lower OS in clear cell renal cell carcinoma." (PMID 34356118, 2021). "All these discoveries showed TIMP1 might be a potential diagnostic and prognostic biomarker for clear cell renal cell carcinoma that facilitated tumor progression." (PMID 35281807, 2022). "In another report, expression of RUNX3 was significantly decreased in 75 cases of clear cell renal cell carcinoma tissues, and RUNX3 inhibited the proliferative and metastatic abilities of clear cell renal cell carcinoma cells by regulating cyclins and TIMP1." (PMID 29651226, 2018). "Therefore, it was considered that the hub gene TIMP1 may play a key role in the progression of clear cell renal cell carcinoma." (PMID 32420905, 2020).